NUP98 (nucleoporin 98 and 96 precursor)
Diseases named in the same sentence as NUP98 in open-access papers (continued):
Sharing a sentence is not in itself a finding about the gene and the disease.
acute myeloid leukemia (continued). "Another example is WHSC1L1, a commonly amplified gene at 8p11-12 in breast and lung cancers; WHSC1L1 is fused with NUP98 in acute myeloid leukemia." (PMID 25537518, 2015). "It has been suggested as an oncogene in breast cancer and plays a role in acute myeloid leukemia as a fusion gene with NUP98." (PMID 25148247, 2014). "NSD1 has been linked to several cancers, including multiple myeloma and lung cancer, and translocations involving NSD1 and NUP98 have been identified in childhood acute myeloid leukemia." (PMID 24874471, 2014). "Translocations that result in fusion of Nup98 to transcription factors lead to acute myeloid leukemias." (PMID 23555195, 2013). "NUP98 gene rearrangements have been reported in acute myeloid leukemia, giving rise to fusion proteins that seem to function as aberrant transcription factors, and are thought to be associated with poor prognosis." (PMID 23332017, 2013). "At least 28 chromosomal rearrangements affecting the NUP98 gene, have been reported in many hematopoietic malignancies, particularly acute myeloid leukemia (AML)." (PMID 23840580, 2013). "NUP98-HOXA9 is an oncogenic fusion protein associated with acute myeloid leukemia (AML) that consists of an N-terminal, FG repeat-rich portion of the nucleoporin NUP98 fused to the homeodomain region of HOXA9." (PMID 19696924, 2009). "Moreover, DDX10 participates in oncogenic fusion events, most notably the NUP98::DDX10 fusion identified in a subset of acute myeloid leukemias, which drives leukemogenesis by disrupting transcriptional regulation and cellular differentiation." (PMID 41751522, 2026). "Summary of both cases of acute myeloid leukemia with NUP98::TNRC18 fusion." (PMID 40264981, 2025). "This suggests that treatment options for NUP98 rearranged acute myeloid leukemia may be adaptable to NUP214 rearranged acute myeloid leukemia patients but further evidence is needed." (PMID 37901324, 2023). "A chimeric fusion between the C-terminal PHD3 domain of KDM5A and nucleoporin 98 (NUP98) is frequently observed in acute myeloid leukemia (AML) cells and promotes malignant transformation." (PMID 40545232, 2025). "For instance, the NUP98 fusion chimeric transcription factor in pediatric acute myeloid leukemia (AML) modifies the formation of condensed structures, hence influencing the expression of genes associated with leukemia." (PMID 39838405, 2025). "Furthermore, NUP98/HOXC13 is of pathogenetic importance in acute myeloid leukemia." (PMID 30884206, 2019). "In adult and pediatric hematological malignancies (such as acute myeloid leukemia (AML) and acute erythroid leukemia (AEL)), NUP98 is commonly fused to various proteins associated with gene regulation." (PMID 31167414, 2019). "Chromosomal translocations involving the nucleoporin NUP98 have been described in several hematopoietic malignancies, in particular acute myeloid leukemia (AML)." (PMID 27031510, 2016). "In acute myeloid leukemia (AML), KDM5A has been shown to form a fusion protein with a nucleoporin 98 gene (NUP98), and over-expression of this fusion protein alone is sufficient to induce AML in murine models." (PMID 24489688, 2014). "Treating pediatric acute myeloid leukemia (AML) with NUP98 rearrangement (NUP98-R) is challenging." (PMID 40016600, 2025). "To demonstrate the utility of our in-house developed qRT-PCR assay to detect the presence of NUP98::NSD1 oncogenic fusion in patients, we screened 150 acute myeloid leukemia (AML) patients." (PMID 36553008, 2022). "The Nup98 fusion protein alters gene expression resulting in Acute Myeloid Leukemia (AML)." (PMID 36589746, 2022). "The NUP98-HOXD13 (NHD13) fusion gene, which is constructed with nucleoporin 98KDa (NUP98) amino terminus and human homeobox 13 (HOXD13) fusion gene, occurs in MDS or acute nonlymphocytic leukemia patients." (PMID 29228688, 2017).
acute myeloid leukemia (continued). "In acute myeloid leukaemia (AML), fusion proteins of NUP98:HOXC11 and NUP98:HOXD13 have been identified which result in aberrant HOX trans-regulatory activity." (PMID 25860510, 2015). "Clustered Hox genes have repeatedly been identified in acute myeloid leukemia (AML) harboring translocations that generate novel fusion proteins containing the N terminal region of the nucleoporin gene, NUP98, and the C terminal Hox region including the homeodomain (HD)." (PMID 17712416, 2007). "In acute myeloid leukemia (AML), the NUP98-HOXA9 fusion utilizes the phase separation-prone domains of NUP98 to form ectopic nuclear bodies." (PMID 41596484, 2026). "For instance, the NUP98 rearrangement, which was not part of the acute myeloid leukemia (AML) with recurrent genetic abnormalities category in the fourth edition of the WHO classification, was introduced into the fifth edition of the WHO classification." (PMID 39001529, 2024). "Nup98-fusions are found most frequently in acute myeloid leukemia (AML), while Nup214-fusions are detected in T-cell acute lymphoblastic leukemia (T-ALL) as well as in AML." (PMID 31755865, 2019). "Interestingly, the upstream region of human NUP96 is the NUP98 coding region, and NUP98 chromosomal translocation (fusion with the Homeobox A9 (HOXA9) gene) has been observed in patients with acute myeloid leukemia (AML)." (PMID 39080077, 2024).
myelodysplastic syndrome (19 papers, 2012 to 2025). A clonal hematopoietic disorder characterized by dysplasia and ineffective hematopoiesis in one or more of the hematopoietic cell lines. "Transduction of either Nup98-Hoxa9 or Nup98-Hoxd13 caused myelodysplastic syndrome which progressed to acute leukemia after long latency periods." (PMID 23326393, 2013). "We used a murine pre-clinical model of myelodysplastic syndrome based on transplantation of cells expressing a NUP98::HOXD13 transgene to investigate 5-Aza-4'-thio-2'-deoxycytidine (Aza TdCyd or ATC), a thiol substituted DNMTi, as a potential therapy." (PMID 38168433, 2023). "One of these is DDX10 which, like Psip1/Ledgf, is found as a fusion partner with Nup98 in myeloid leukaemias and myelodysplastic syndromes, perhaps indicative of their function in a common pathway that is mis-regulated in these malignancies." (PMID 22615581, 2012). "While the FLT3/ITD mutation alone induces a lethal myeloproliferative neoplasm (MPN) and the Nup98-HoxD13 translocation alone produces a myelodysplastic syndrome (MDS), mice bred to express both mutations develop an acute leukemia with short latency and 100% penetrance." (PMID 22643831, 2012). "Notably, different Nup98 fusions trigger slightly different phenotypes in HPCs, ranging from myelodysplastic syndrome to T-cell acute lymphoblastic leukemia to AML." (PMID 29269482, 2017). "While NUP98 translocations are seen in myelodysplastic syndrome (MDS), AML, blast-phase chronic myelogenous leukemia (CML), and t-ALL, NUP98 translocations are exceedingly rare in myeloproliferative disorders." (PMID 38443661, 2024). "Furthermore, genetic fusions of NSD3 with NUP98 and NUTM1 genes have been described in patients with AML as well as myelodysplastic syndrome, and primary pulmonary NUT carcinoma, respectively." (PMID 37062069, 2023).
viral infection (14 papers, 2006 to 2024). "Among NUPs, NUP98 is shown as one of the interferon-stimulated genes (ISGs) and is implicated in antiviral gene expression to limit viral infection in a Drosophila model." (PMID 38449868, 2024). "In these cases, the NUP98 protein was shown to be targeted during viral infection by several mechanisms including phosphorylation, degradation, or specific cleavage, thus reducing intracellular NUP98 levels." (PMID 38449868, 2024). "Together, these data indicate that the Sarbecovirus accessory protein ORF6 prevents bidirectional nucleocytoplasmic transport through its interactions with Rae1 and Nup98, leaving host cells incapable of responding to viral infection." (PMID 33849972, 2021). "Nup98/Gle2-dependent mRNA export is therefore critical for resistance to viral infections and appears to be a preferred target of viruses." (PMID 25184662, 2014). "However, it is worth mentioning that NUP98 is an interferon-inducible transcription factor and plays a critical role in host immune response against viral infection." (PMID 31396490, 2019). "Nup98 is an important nucleoporin mediating nuclear translocation of mRNAs in viral infection." (PMID 28018858, 2016). "We found that several interactors of the host proteins are differentially expressed upon viral infection, are related to highly relevant pathways, and that the novel interaction of NUP98 with CHMP5 may activate an antiviral mechanism leading to disruption of viral budding." (PMID 32702714, 2020). "Our studies here provide evidence to demonstrate coordination between NUP98 and NRG1-ERBB4/PSEN1 signaling proteins in the host response to viral infection and identify a previously unrecognized mechanism of enteroviral pathogenesis of viral myocarditis." (PMID 31396490, 2019). "Differentially expressed genes in the viral infection category (174 genes) indicated that keratinocytes had down-regulated genes involved in host gene transcription (DDX56, SMARCA2) and RNA transportation and processing (NUP98, RAE1, XAB2, RBM17, EXOSC10)." (PMID 34552595, 2021). "Intriguingly, ectopic expression of viral protease 3C in the absence of viral infection appeared to induce the upregulation and redistribution of NUP98 to the nucleoplasm, as compared to vector transfected cells where NUP98 is observed mostly at the nuclear periphery (see Discussion)." (PMID 31396490, 2019). "There were, however, differences between the two cell types tested; for example, RPS14 knockdown strongly inhibited viral infection in NHBE but not A549 cells, and knockdown of NUP98 was inefficient in NHBE cells despite inhibiting virus in A549 cells." (PMID 29775471, 2018).
acute leukemia (11 papers, 2012 to 2025). A clonal (malignant) hematopoietic disorder with an acute onset, affecting the bone marrow and the peripheral blood. "Recent work has shown that FLT3 activating mutations can collaborate with a Nup98-HoxD13 mutation to induce an aggressive acute leukemia." (PMID 22643831, 2012). "The LLPS of an aberrant chimera NUP98-HOXA9, generated by recurrent chromosomal translocation of NUP98, can bind to and enhance the activation of target genes, promoting the development of acute leukemia." (PMID 39749343, 2024). "The interaction between menin and MLL1 has been implicated in the development of acute leukemias driven by MLL1/KMT2A rearrangements (MLL1-r), NPM1 mutations (NPM1-mut), and NUP98 rearrangements (NUP98-r)." (PMID 39276940, 2024). "NUP98 fusions are predominantly linked to myeloid malignancies such as AML, chronic myeloid leukemia in blast crisis and mixed phenotype acute leukemia." (PMID 39323480, 2024). "Menin inhibitors disrupt the menin-KMT2A complex in preclinical models of KMT2A-r, NUP98-r and NPM1c acute leukemias and its occupancy at target genes leading to leukemic cell differentiation and apoptosis." (PMID 38174649, 2023). "NUP98 is frequently fused to a variety of genes in pediatric acute leukemias through translocations or inversions, for instance it can fuse to the PHD domain of KDM5A, forming NUP98-KDM5A." (PMID 34944554, 2021). "This phase I trial investigated the safety of revumenib in combination with chemotherapy (FLA regimen) in both adults and children with KMT2A-r, NUP98-r, or NPM1-m acute leukemia." (PMID 41154380, 2025). "Bleximenib, for instance, is currently being tested in a pediatric cohort (12 years and older) of the phase 1/2 study (cAMeLot-1) for acute leukemia patients harboring KMT2A, NPM1, NUP98, or NUP214 alterations (NCT04811560)." (PMID 41154380, 2025). "Lastly, the clinical application of menin inhibitors is gradually expanding to include other acute leukemia subtypes characterized by MEIS1-HOXA axis activation, such as specific AML subgroups with particularly poor prognosis like NUP98-r, DEK-NUP21, and UBTF-TD." (PMID 40710017, 2025).
chronic myeloid leukemia (10 papers, 2014 to 2024). "Early studies focused on its role in hematological malignancies based on observations from several groups of its involvement in fusions with the NUP98 protein generated by chromosomal translocations in patients with acute and chronic myeloid leukemia." (PMID 32127038, 2020). "Severe osteoblastic defects were found in a model of myeloid blast-crisis chronic myeloid leukemia (CML, driven by BCR-ABL;Nup98/HoxA9), with decreased osteoprogenitors, endosteal-lining osteoblasts and bone mass, associated with increased CCL3 expression." (PMID 27436341, 2017).
acute lymphoblastic leukemia (8 papers, 2010 to 2024). Leukemia with an acute onset, characterized by the presence of lymphoblasts in the bone marrow and the peripheral blood. "Interestingly, ADD3 was also detected in acute lymphoblastic leukemia as a fusion protein with NUP98." (PMID 21118496, 2010). "We previously identified NUP98-BPTF (NB) fusion in patients with T-cell acute lymphoblastic leukemia (T-ALL) using next-generation sequencing." (PMID 38940430, 2024). "HOXA9 is linked to impaired differentiation of hematopoietic precursor cells and is frequently activated in mixed-lineage leukemia (MLL)-related AML and ALL, T-cell acute lymphoblastic leukemia (T-ALL) and in Nup98-rearranged AML." (PMID 28471392, 2017). "Recurrent rearrangements at 11q15.4 involving the gene Nucleoporin 98 and 96 precursor (NUP98) are found in a variety of hematologic neoplasias, such as AML, myelodysplastic neoplasias (MDS), and T-cell acute lymphoblastic leukemia (T-ALL)." (PMID 37296904, 2023).
breast carcinoma (8 papers, 2014 to 2024). "We used siRNA to NUP98-96 in MCF7 breast cancer cells and PC3 prostate cancer cells for 72 h and compared effects on Nup98 protein levels, protein synthesis and pJNK to a control scrambled siRNA." (PMID 35107131, 2022). "Investigation into the role of NUP98 as a biomarker in breast cancer as a whole showed similar trends to TNBC especially within Luminal B,HER2 negative cases." (PMID 30935371, 2019). "While trends linking NUP98 expression with poorer outcomes were observed in breast cancer overall (and more specifically in the LuminalB Her2- subgroup), significant correlations were observed in TNBC." (PMID 30935371, 2019). "NUP98 protein expression was then analysed in the context of survival in breast cancer as a whole as well as within the subtypes." (PMID 30935371, 2019). "Hypermethylation of the promoters of tumor suppressor genes ATM, NOTCH1, NUP98, PALB2, TSC2, and WRN had all previously been associated with WTC exposure and were again observed to be hypermethylated in WTC EHC compared to NYUWHS breast cancer patients." (PMID 35564499, 2022). "However, NUP98, where is circNUP98 derived from, acted as an oncogene in haematological cancers and breast cancer." (PMID 32729669, 2020). "We next wanted to investigate whether the role for NUP98 as a biomarker to predict response to SoC was restricted to TNBC or could be applied to breast cancer as a whole." (PMID 30935371, 2019). "Using the online tool, KM Plotter, a significant association with poor relapse free survival and high NUP98 expression was only observed when patients who did not receive systemic treatment were excluded in both breast cancer as a whole and TNBC." (PMID 30935371, 2019). "The CDK4/6 inhibitor palbociclib, which is approved for the treatment of breast cancer, demonstrated potent anti‐proliferative activity and differentiation induction in murine AML cells driven by NUP98::KDM5A, NUP98::DDX10, and NUP98::NSD1, as well as in human NUP98‐r leukemic cells." (PMID 39323480, 2024). "However, the distribution of NUP98 expression varied significantly (chi-squared p = < 0.0001) between subtypes of breast cancer (defined by the St Gallen surrogate classification method) with only the TNBC samples showing a substantial proportion of samples with no NUP98 expression." (PMID 30935371, 2019).
acute megakaryoblastic leukemia (7 papers, 2018 to 2026). Acute megakaryoblastic leukemia (AMKL) is a form of acute myeloid leukemia (AML) that occurs predominantly in childhood and particularly in children with Down syndrome (DS-AMKL). "These regions might reflect lineage-specific characteristics associated with acute megakaryocytic leukemia (M7) diagnosed in these NUP98::KDM5A-expressing samples." (PMID 40389480, 2025). "In particular, the NUP98::BPTF fusion has been detected in a patient with acute megakaryoblastic leukemia." (PMID 41419605, 2026). "The JARID1A (KDM5A) H3K4 demethylase is fused to NUP98 in approximately 10% of pediatric acute megakaryoblastic leukemia resulting in the cytogenetically cryptic NUP98–JARID1A translocation." (PMID 29527516, 2018). "Moreover, a NUP98-BPTF gene fusion in which a C-terminal chromatin recognition module of BPTF is fused to the N-terminal moiety of NUP98 has been identified in primary refractory acute megakaryoblastic leukemia (AMKL) that contributes to refining the NUP98 rearrangement subgroup of pediatric AMKL." (PMID 34736517, 2021). "Although the NUP98::KDMA5 fusion is less frequent, occurring in only 1.4% of pediatric AML cases, its relevance increases in specific subtypes, such as acute megakaryoblastic leukemia (AMKL), where it is present in 10% of patients." (PMID 39323480, 2024).
myeloid leukemia (7 papers, 2012 to 2025). A clonal proliferation of myeloid cells and their precursors in the bone marrow, peripheral blood, and spleen. "Thus far the NH9 fusion oncogene has been exclusively linked with myeloid leukaemias, but other Nup98 fusion proteins have been identified in cases of human paediatric T-ALL36–38." (PMID 30538250, 2018). "UF1852 (PB) was diagnosed with myeloid leukemia associated with Down Syndrome and predicted as AML with NUP98 fusion (0.957)." (PMID 39711573, 2024). "For example, previous studies have shown that transplantation of lin− HSPCs expressing NHA9 and other NUP98 FOs into recipient mice results in the development of myeloid leukemia." (PMID 34903620, 2022).
T-cell acute lymphoblastic leukemia (6 papers, 2010 to 2024). Acute lymphoblastic leukemia of T-cell origin. "It was reported that translocation fusion of the NUP98 and RAP1GDS1 genes was recurrent in T-cell acute lymphocytic leukemia." (PMID 21114830, 2010).
acute promyelocytic leukemia (5 papers, 2013 to 2024). An aggressive form of acute myeloid leukemia (AML), characterized by arrest of leukocyte differentiation at the promyelocyte stage, due to a specific chromosomal translocation t(15;17) in myeloid cells. "In summary, we reported 1 case of acute myeloid leukemia with the NUP98/RARG fusion gene and the RUNX1 mutation that resembled acute promyelocytic leukemia in regards to its morphologic and immunologic features." (PMID 33019444, 2020). "NUP98-RARG and NUP98-RARA have clinical phenotypes of acute promyelocytic leukemia with similar bone marrow morphologies, coagulation abnormalities, and immunophenotypes." (PMID 38443661, 2024).
acute erythroid leukemia (4 papers, 2019 to 2025). An acute myeloid leukemia characterized by a predominant immature erythroid population. "NUP98 rearrangements are also relatively common in the rare M6 subtype (acute erythroid leukemia), where they are found in about one-third of the cases." (PMID 41155189, 2025). "Program P2 (with undefined association to killing) was significantly enriched in FAB subtypes M5 (q < 0.05) and M6 (acute erythroid leukemia) and WHO subtypes AML with KMT2A, and NUP98 rearrangement, which has a poor prognosis." (PMID 38724673, 2024).